OR2B8 (olfactory receptor family 2 subfamily B member 8 (gene/pseudogene))
Description:
Odorant receptor.
Synonyms: OR2B8P; hs6M1-29P; OR6-10; dJ313I6.4
Gene: Protein-coding gene on chromosome 6 (28,053,228 to 28,054,165, reverse strand). Ensembl gene ENSG00000182477.
Subcellular location: Cell membrane
Diseases named in the same sentence as OR2B8 in open-access papers:
OR2B8 is named in the same sentence as 2 diseases in open-access papers, as found by Europe PMC text mining. Sharing a sentence is not in itself a finding about the gene and the disease.
OR2B8 shares sentences with these, for which no sentence is quoted: cervical cancer (1 paper); tumor (1).